CXCR4 (C-X-C motif chemokine receptor 4)
Diseases named in the same sentence as CXCR4 in open-access papers (continued):
Sharing a sentence is not in itself a finding about the gene and the disease.
hepatocellular carcinoma (continued). "In these samples, 4 were stained as weakly positive, 2 were masculine positive, and CXCR4 was located mainly in the membrane and cytoplasm of hepatoma cells." (PMID 21110890, 2010). "Numerous studies have demonstrated that CXCR4 frequently overexpressed in a variety of human tumors, such as breast cancer, prostate cancer and hepatocellular carcinoma." (PMID 20380740, 2010). "To explore the role of CXCR4 in hepatoma cells, we performed an experiment with invasiveness in transwells in the 24-well culture plate using the cell invasion assay kit." (PMID 21110890, 2010). "The human hepatoma cell lines analysed revealed different intensities of a predominantly cytoplasmatic CXCR4 expression." (PMID 16819541, 2006). "Splenic lymphocytes revealed a strong CXCR4 expression matching human hepatocellular cancer tissue or cell lines with strong expression of CXCR4." (PMID 16819541, 2006). "Three previous studies also identified nuclear localization of CXCR4 in hepatocellular carcinoma, invasive ductal mammary carcinoma and non-small-cell lung cancer (NSCLC)." (PMID 15978137, 2005). "Blocking CXCR4 in combination with anti–PD–1 therapy enhances antigen presentation and increases cDC1 infiltration into tumors, as demonstrated in orthotopic and autochthonous hepatocellular carcinoma (HCC) models." (PMID 40667699, 2025). "Although miR-452-3p has been established as a tumorigenic factor in diseases like hepatocellular carcinoma, its upregulation in microglia correlating with downregulation of CXCR4 expression suggests a potential anti-inflammatory role, yet its function in IS remains elusive." (PMID 39897488, 2025). "In the pre-metastatic microenvironment of hepatocellular carcinoma, the expression of CXCL12 can downregulate the transcription factor Paired Related Homeobox 1 (Prrx1), thereby inducing an increase in the protein and mRNA expression of CXCR4 in hepatocellular carcinoma cells via the STAT3 pathway." (PMID 38920657, 2024). "Transcription factor 12 (TCF12) could directly bind to the CXCR4 promoter to up-regulate the expression of CXCR4, thereby enhancing the proliferation, migration, and invasion of hepatocellular carcinoma cells." (PMID 37497001, 2023). "Based on this, researchers developed lipid nanoparticles consisting of G0-C14, PLGA, and lipid PEG and modified them with CTCE-9908, a targeting peptide specific to CXCR4 (which is highly expressed in hepatocellular carcinoma cells) to achieve specific targeting of hepatocellular carcinoma cells." (PMID 36559175, 2022). "Matrix metalloproteinase 10 promotes angiogenesis, growth, and diffusion of human hepatocellular carcinomas by regulating the CXCL12/CXCR4 axis, and the phosphatase and tensin homolog can negatively regulate the expression of CXCL12/CXCR4 in prostate tumors, thereby controlling tumor growth." (PMID 33710803, 2021). "Moreover, CXCL12 and CXCR4 polymorphisms appear to contribute to increased risk of hepatocellular carcinoma (HCC) and may be potential markers for HCC." (PMID 33363463, 2020). "Furthermore, more studies are needed to explore the specific function of the CXCL12/CXCR4/CXCR7 axis in hepatocellular cancer." (PMID 30574021, 2018). "Furthermore, we showed that autologous chemotaxis influences this interstitial fluid flow-induced invasion of hepatocellular carcinoma derived cell lines via the C-X-C chemokine receptor type 4 (CXCR4)/C-X-C motif chemokine 12 (CXCL12) signaling axis." (PMID 26560447, 2015). "Therapeutic intervention with CXCR4 signal activation could be used as a promising strategy against hepatocellular carcinoma after curative resection." (PMID 26404566, 2015).
hepatocellular carcinoma (continued). "Prolonged exposure to TGF-β induces rat hepatocellular carcinoma cells to exhibit a mesenchymal phenotype, and a higher migratory and invasive capacity, coincident with increased CXCR4 expression, and these phenotypic changes are reduced by a CXCR4 antagonist." (PMID 24966464, 2014). "Therefore, we analysed the expression profile of CXCR4 in a series of human hepatoma cell lines and HCC patients." (PMID 16819541, 2006). "The chemokine, C-X-C motif chemokine ligand 12 (CXCL12) and its G-protein-coupled receptor (GPCR) and C-X-C chemokine receptor type 4 (CXCR4), are closely associated with promoting hepatocellular carcinoma (HCC) chemotaxis and metastasis." (PMID 37251542, 2023). "Thus, this study suggests that CXCR4 may be a potential target for hepatocellular carcinoma treatment." (PMID 34555268, 2021). "In hepatocellular carcinoma (HCC), CXCR4 is expressed in tumor endothelium sprouting tumor vessels and CXCR4-positive ECs predict sorafenib susceptibility." (PMID 33937018, 2021). "High levels of CXCL12 and CXCR4 were reported in sinusoidal endothelial cells in Hepatocellular Carcinoma (HCC) specimens." (PMID 32260318, 2020). "Reduced AFP in the AFP-siRNA transfected, ChIP results indicated that human hepatoma PLC/PRF/5 cells were transfected with AFP-siRNA vectors led to an apparent reduction of binding of p-mTOR(Ser2448) to the promoter elements in the 5′-flanking region of the CXCR4 gene compared to the input." (PMID 25815363, 2015). "Moreover, decreased production of CXCR4 and MMP-2 in association with lower invasion of hepatocellular carcinoma cells could be related to the down-regulation of metastasis." (PMID 21909361, 2011). "In hepatocellular carcinoma, the activation of the CXCL12/CXCR4 axis via the STAT3 signaling pathway promotes protein expression of CSC markers SOX2 and CD133, enhancing the spheroid-forming capacity and invasiveness of liver cancer cells." (PMID 38920657, 2024). "On the other hand, clinical sorafenib treatment can activate the C-X-C receptor type 4 (CXCR4)/stromal-derived factor-1α (SDF-1α) axis, aggravate intratumoral hypoxia in hepatocellular carcinoma (HCC), and further lead to hepatocellular carcinoma." (PMID 37576900, 2023). "Another CXCR4 antagonist, BPRCX807, has been shown to be effective in inhibiting migration and suppressing metastasis in hepatocellular carcinoma." (PMID 36140541, 2022). "It has been demonstrated that IIN concerning IgA production is involved in some types of cancer, such as hepatocellular carcinoma, which can be activated by CCR9, CCR10, and CXCR4 to promote tumor growth and metastases." (PMID 35883015, 2022). "A highly selective, safe, and potent CXCR4 antagonist, BPRCX807, has been designed and experimentally validated in various hepatocellular carcinoma models." (PMID 33753481, 2021). "Furthermore, hBMMSCs were shown to mediate osteosarcoma and hepatocellular carcinoma (HCC) cell migration and invasion through the regulation of CXCR4." (PMID 33849537, 2021). "These include evaluation of the CXCL12/CXCR4 axis in angiogenesis, the CCL20/CCR6 axis in the growth of the hepatoma cell line Huh7; and the CCL5/CCR1 axis in promoting the metastasis and invasion of HCC cells." (PMID 32260550, 2020). "Suppression of CXCR4 activity via CXCR4 knockdown, AMD3100 or neutralizing antibody administration inhibits hepatoma cell tumorigenesis in vitro and in vivo." (PMID 26404566, 2015). "This is the first study exploring the effect of CCR7 on TGF-β1-induced EMT and coincides with a recent report demonstrating crosstalk between CXCR4 and TGF-β-induced EMT in hepatocellular carcinoma." (PMID 26176983, 2015). "The aim of our study was to elucidate the effect of tacrolimus (FK506) and of C-X-C chemokine receptor type 4 (CXCR4), which is a receptor specific to the stromal cell-derived factor-1α (SDF-1α), on growth and metastasis of hepatocellular carcinoma (HCC)." (PMID 24912495, 2014).
hepatocellular carcinoma (continued). "Previous study indicated that CXCR4 were highly expressed in HCC, and its ligand chemokine (C-X-C motif) ligand 12 (CXCL12) CXCL12 can stimulate human hepatoma cell growth, migration and invasion." (PMID 24586606, 2014). "Osteopontin up-regulates MMP-2 through activating the SDF-1α/CXCR4 axis, mediated by binding to integrin αvβ3 and CD44v6 and activating the PI3K/Akt and JNK pathways in hepatocellular carcinoma cells (HepG2 and SMMC7721)." (PMID 21909361, 2011). "The rhOPN-induced CXCR4 expression is dependent on CD44 and integrin receptors, and is regulated by the PI-3K/Akt and JNK pathways in the two hepatocellular carcinoma cell lines (HepG2 and SMMC7721) tested." (PMID 21909361, 2011). "Therefore, we evaluated, if the expression of CXCR4 exerts similar effects in human hepatocellular carcinoma (HCC)." (PMID 16819541, 2006). "Likewise, the secretome of CAFs separated from hepatocellular carcinoma (HCC-CAF) leads to the recruitment and activation of neutrophils in TME via the SDF1a/CXCR4 signaling pathway." (PMID 36275750, 2022). "In our previous report, we have studied the CTCs in hepatocellular carcinoma (HCC) and shown that CD90+CXCR4+ HCC cells may be CTCs and selective elimination of these cells may substantially improve the current HCC therapy by reducing cancer metastasis." (PMID 30844765, 2019). "In hepatocellular carcinoma (HCC), sorafenib treatment induces SDF1α expression in the stroma, which in turn activates hepatic stellate cells (HSCs) and Gr+ myeloid cell infiltration through a CXCR4-dependent pathway." (PMID 30927928, 2019). "Since hepatocytes/hepatoma cells are CD4-negative cells, by flow cytometry we measured the effects of AGS on expression the candidate receptors for HIV entry on hepatocytes, namely, CXCR4, CCR5 and GalCer (galactosyl ceramide)." (PMID 31835520, 2019). "In the case of hepatocellular carcinoma the intracellular expression of CXCR4 with lack of its expression at the cell surface and lack of response to its ligand CXCL12 has been reported." (PMID 24559071, 2014). "The observation that rhOPN induced SDF-1α, CXCR4 and MMP-2 expression in human hepatocellular carcinoma cells suggested that the SDF-1α/CXCR4 axis might play a role in osteopontin-dependent tumor progression." (PMID 21909361, 2011). "In comparison with untreated cells, recombinant human osteopontin (rhOPN) up-regulated CXCR4, SDF-1α, and MMP-2 expression about 5-, 4-, and 6-fold on the protein levels through binding to integrin αvβ3 and CD44v6 in hepatocellular carcinoma cells (SMMC7721 and HepG2)." (PMID 21909361, 2011). "Schimanski and colleagues found that dissemination of hepatocellular carcinoma (HCC) may be mediated via the chemokine receptor CXCR4, but the relationship between CXCR4 expression and bone metastases of HCC remains unknown." (PMID 19508713, 2009). "Chemokines and their receptors, acting as axes such as CXCL12/CXCR4, play a crucial role in shaping the tumor microenvironment (TME) and influence the progression of hepatocellular carcinoma (HCC)." (PMID 40145607, 2025). "However, chronic hypoxia does not universally induce CXCR4 expression in tumor cells—for example, in hepatocellular carcinoma cells it only increases the expression of CXCR4 in some cell lines." (PMID 33467722, 2021). "Sorafenib is approved as a standard therapy for advanced hepatocellular carcinoma (HCC), but its clinical application is limited due to moderate therapeutic efficacy and high incidence of acquired resistance resulted from elevated levels of SDF-1/CXCR4 axis induced by prolonged sorafenib treatment." (PMID 31151472, 2019). "Indeed, the combination of the small CXCR4 antagonist, AMD3100, with the multikinase inhibitor sorafenib and anti-PD-1 treatment enhanced CD8 T cell mediated antitumor immunity in a mouse model of advanced hepatocellular carcinoma (HCC)." (PMID 30591657, 2018).
hepatocellular carcinoma (continued). "CXCR4, stromal cell-derived factor-1α(SDF 1α) receptor, stimulates growth and metastasis of hepatocellular carcinoma (HCC)." (PMID 25815363, 2015). "We detected differential expression of CXCR4 between PVTT and hepatocellular carcinoma (HCC) by an immunohistochemical assay." (PMID 21110890, 2010). "Plerixafor targets CXCR4, but this might not occur in hepatocellular carcinoma (HCC) cells." (PMID 36891156, 2023). "To further elucidate the role of the SDF-1α/CXCR4 axis in human hepatocellular carcinoma, we detected the expression and activity of MMP-2 induced by 50 nM rhOPN in the presence or absence of SDF-1α neutralizing antibody, CXCR4 inhibitor 12G5, or CXCR4 inhibitor AMD3100." (PMID 21909361, 2011).
acute myeloid leukemia (117 papers, 2007 to 2026). Acute myeloid leukemia (AML) is a group of neoplasms arising from precursor cells committed to the myeloid cell-line differentiation. "In contrast, CXCR4 expression was negatively associated with OS in acute myelogenous leukemia (left)." (PMID 37749552, 2023). "A number of authors have shown that high CXCR4 expression levels in infused NK cells was associated with an increased probability of objective response in patients with relapsed/refractory acute myeloid leukemia or high-risk myelodysplastic syndrome." (PMID 36685552, 2022). "Long term safety data for the first generation of CXCR4 antagonists used for patients with acute myeloid leukemia, where a high CXCR4 expression is linked to poor progression, demonstrates that CXCR4 inhibition is a well-tolerated approach." (PMID 32843095, 2020). "Overexpression of CXCR4 is a hallmark of many hematological malignancies including acute myeloid leukemia, chronic lymphocytic leukemia and non-Hodgkin’s lymphoma, and generally correlates with a poor prognosis." (PMID 26954567, 2016). "Pim-1 overexpression has been associated with upregulated cell surface expression of CXCR4 in hematopoietic malignancies such as acute myeloid leukemia, diffuse large B-cell lymphoma and chronic lymphocytic leukemia." (PMID 26075720, 2015). "Similarly, genotyping 466 acute myeloid leukemia patients and 460 healthy controls indicates that a polymorphism in rs2228014 in the CXCR4 coding sequence is significantly increased in AML patients relative to healthy controls." (PMID 33363463, 2020). "The association of acute myelogenous leukemia (AML) cells with the bone marrow microenvironment may be mediated by CXCR4, which is invariably expressed on AML blasts." (PMID 27429863, 2015). "Consistent with this, it has been shown that inhibition of TGF-β and CXCR4 results in improved survival in an fms-related receptor tyrosine kinase 3 (flt3)-mutated acute myeloid leukemia (AML) model." (PMID 38396852, 2024). "HDACs cause hyperacetylation and therefore destabilization for the chaperone protein heat shock protein 90 (HSP90), which inhibits its association with CXCR4 leading to proteasomal degradation of CXCR4 in acute myeloid leukemia (AML) cells." (PMID 36986514, 2023). "For example, CXCR4 is overexpressed in 25–30% of patients with acute myeloid leukemia (AML) and is associated with poor prognosis." (PMID 33669329, 2021). "There have been successful clinical applications of chemokine therapies, such as the CXCR4 antagonist AMD3100 for treating relapsed or refractory acute myeloid leukemia (AML) and the CCL2 inhibitor CNTO 888 for metastatic prostate cancer." (PMID 39206194, 2024). "The acute myeloid leukemia patients with high levels of CXCR4 and low expressions of miR-9 showed poor prognosis." (PMID 38473229, 2024). "The CXCL12/CXCR4 produced by Prx1+ mesenchymal cells can be a target to eradicate parenchymal leukemia stem cells (LSCs) in acute myeloid leukemia (AML)." (PMID 38841622, 2024). "The authors also demonstrated that miR-9 directly targets CXCR4, with the miR-9/CXCR4 axis emerging as a critical factor and potential therapeutic target in acute myeloid leukemia pathology." (PMID 38473229, 2024). "UCA1 stabilizes METTL14 allowing the writer to deposit m6A marks on target mRNAs, such as CYP1B1 and CXCR4, leading to acute myeloid leukemia (AML) development." (PMID 39280246, 2024). "The authors found that miR-9 and CXCR4 (C-X-C chemokine receptor 4) were differentially expressed in acute myeloid leukemia samples, showing an inverse correlation between miR-9 and CXCR4 (right)." (PMID 38473229, 2024). "The co-regulation of the expression of uPAR and the chemokine receptor CXCR4 has been observed in acute myeloid leukemia (AML) cells and blasts; in fact, both receptors are directly targeted by the same miRs, i.e., miR-335, miR-146a and miR-622." (PMID 36674481, 2023).